ANKRD13B (ankyrin repeat domain 13B)
Description:
Ubiquitin-binding protein that specifically recognizes and binds 'Lys-63'-linked ubiquitin. Does not bind 'Lys-48'-linked ubiquitin. Positively regulates the internalization of ligand-activated EGFR by binding to the Ub moiety of ubiquitinated EGFR at the cell membrane.
Synonyms: FLJ25555
Tractability: Antibody: UniProt places it where antibodies can reach, with high confidence; its Gene Ontology location is reachable by antibodies, with high confidence; the Human Protein Atlas places it where antibodies can reach. PROTAC: ubiquitination databases record sites on it.
Gene: Protein-coding gene on chromosome 17 (29,589,769 to 29,614,761, forward strand). Ensembl gene ENSG00000198720.
Subcellular location: Cell membrane; Late endosome; Early endosome
Subcellular location (Human Protein Atlas): Vesicles; Plasma membrane
Gene Ontology:
Molecular function: ubiquitin-modified protein reader activity
Biological process: negative regulation of receptor internalization; regulation of receptor-mediated endocytosis
Cellular component: cytoplasm; early endosome; late endosome; perinuclear region of cytoplasm; plasma membrane
Genetic constraint (gnomAD): Loss-of-function variants: 32 observed, 64.01 expected, observed/expected ratio (o/e) 0.5, 90% interval 0.38 to 0.67. The upper end of that interval is the gene's LOEUF score, 0.67, which puts it in group 2 of 6, group 1 being the genes least tolerant of losing a copy. Missense variants: 676 observed, 788.45 expected, observed/expected ratio (o/e) 0.86, 90% interval 0.8 to 0.91. Synonymous variants: 341 observed, 318.33 expected, observed/expected ratio (o/e) 1.07, 90% interval 0.98 to 1.17.
Homologues: Orthologues: chimpanzee ANKRD13B (99% identical), dog ANKRD13B (99% identical), pig ANKRD13B (98% identical), mouse Ankrd13b (97% identical), guinea pig ANKRD13B (93% identical), rat Ankrd13b (90% identical), macaque ANKRD13B (89% identical), tropical clawed frog ankrd13b (80% identical), rabbit ANKRD13B (74% identical), zebrafish ankrd13b (71% identical), Drosophila melanogaster CG15118 (44% identical), Caenorhabditis elegans C18F10.7 (33% identical). Paralogues in human: ANKRD13D (63% identical), ANKRD13A (50% identical), ANKRD13C (26% identical).
Diseases named in the same sentence as ANKRD13B in open-access papers:
ANKRD13B is named in the same sentence as 6 diseases in open-access papers, as found by Europe PMC text mining. Sharing a sentence is not in itself a finding about the gene and the disease. The quoted sentences say what the papers report.
bladder cancer (1 paper, 2022). "Based on our data, we suggest that ANKRD13B could act as a marker of high-risk bladder cancer, since its expression was significantly elevated in these cancers." (PMID 35806060, 2022).
Fanconi anemia (1 paper, 2021). Fanconi anemia (FA) is a hereditary DNA repair disorder characterized by progressive pancytopenia with bone marrow failure, variable congenital malformations and predisposition to develop hematological or solid tumors. "Previous studies showed that ANKRD13B and FANCE were associated with epidermal growth factor receptor (EGFR) activation and Fanconi anemia, respectively." (PMID 34917510, 2021).
lung carcinoma (1 paper, 2022). "The function of ANKRD13B, FBXL8, and KBTBD12 in the carcinogenesis and progression of lung cancer need to be further investigated." (PMID 35884544, 2022).
renal cell carcinoma (1 paper, 2022). "ANKRD13B was overexpressed in tumor tissues compared with normal renal tissue, and the higher expression indicated that patients with renal cell carcinoma had an advanced clinical stage and low OS." (PMID 35884544, 2022).
cancer (2 papers, 2021 to 2022). A tumor composed of atypical neoplastic, often pleomorphic cells that invade other tissues. "Among these mRNAs, TMEM164, ZNF607, and ANKRD13B showed significant altered expression across tumor stages, indicating their role in cancer progression and invasion." (PMID 35140741, 2021).
tumor (2 papers, 2021 to 2022). "ANKRD13B, ISG15, KBTBD12, KLHL35, and UHRF1 were upregulated in tumor samples; DCUN1D5, HCK, and SOCS3 were downregulated in tumor than in normal samples." (PMID 35884544, 2022).